VPS37D (VPS37D subunit of ESCRT-I)
Description:
Component of the ESCRT-I complex, a regulator of vesicular trafficking process. Required for the sorting of endocytic ubiquitinated cargos into multivesicular bodies. May be involved in cell growth and differentiation.
Synonyms: WBSCR24; MGC35352
Tractability: Antibody: UniProt places it where antibodies can reach, with high confidence. PROTAC: ubiquitination databases record sites on it; its protein half-life has been measured.
Gene: Protein-coding gene on chromosome 7 (73,667,831 to 73,672,112, forward strand). Ensembl gene ENSG00000176428.
Subcellular location: Late endosome membrane
Subcellular location (Human Protein Atlas): Vesicles
Pathways (Reactome):
Disease: Budding and maturation of HIV virion; HCMV Late Events; Membrane binding and targetting of GAG proteins
Autophagy: Late endosomal microautophagy
Vesicle-mediated transport: Endosomal Sorting Complex Required For Transport (ESCRT)
Gene Ontology:
Molecular function: protein binding
Biological process: macroautophagy; membrane fission; multivesicular body assembly; protein targeting to membrane; protein targeting to vacuole; protein transport to vacuole involved in ubiquitin-dependent protein catabolic process via the multivesicular body sorting pathway; ubiquitin-dependent protein catabolic process via the multivesicular body sorting pathway; viral budding via host ESCRT complex
Cellular component: ESCRT I complex; extracellular exosome; endosome membrane; late endosome membrane
Genetic constraint (gnomAD): Loss-of-function variants: 4 observed, 9.28 expected, observed/expected ratio (o/e) 0.43, 90% interval 0.21 to 0.99. That is too few expected variants to judge how well the gene tolerates losing a copy. Missense variants: 338 observed, 231.11 expected, observed/expected ratio (o/e) 1.46, 90% interval 1.34 to 1.6. Synonymous variants: 151 observed, 101.97 expected, observed/expected ratio (o/e) 1.48, 90% interval 1.3 to 1.7.
Homologues: Orthologues: chimpanzee VPS37D (100% identical), macaque VPS37D (100% identical), dog VPS37D (98% identical), pig VPS37D (96% identical), mouse Vps37d (96% identical), rat Vps37d (96% identical), guinea pig VPS37D (92% identical), tropical clawed frog vps37d (44% identical), zebrafish vps37d (40% identical), Drosophila melanogaster Vps37B (24% identical). Paralogues in human: VPS37B (33% identical), VPS37C (33% identical), VPS37A (19% identical).
Diseases named in the same sentence as VPS37D in open-access papers:
VPS37D is named in the same sentence as 7 diseases in open-access papers, as found by Europe PMC text mining. Sharing a sentence is not in itself a finding about the gene and the disease. The quoted sentences say what the papers report.
breast carcinoma (1 paper, 2025). "The VPS37D gene, with significant variation in breast cancer, predicts patient prognosis and is related to the tumor microenvironment, suggesting that ESCRT is a novel biomarker for early diagnosis and prognosis assessment." (PMID 40230849, 2025). "Taken together, these studies highlight the importance of the ESCRT family gene VPS37D in breast cancer initiation, progression, and immune response." (PMID 40230849, 2025). "In breast cancer, VPS37D correlates with clinicopathological factors and the tumor microenvironment." (PMID 40230849, 2025). "In the context of breast cancer, a deep prediction analysis revealed that differential expression of the VPS37D gene has a significant impact on disease prognosis and progression." (PMID 40230849, 2025). "This study used breast cancer as a model to investigate the potential significance of VPS37D and other critical molecules in the remodeling of the tumor microenvironment and precision therapy, thereby offering a theoretical foundation for the advancement of tumor immunotherapy." (PMID 40230849, 2025). "We subsequently validated the protein expression of VPS37D in the HPA database, and the results showed that it was highly expressed in breast cancer tissues compared to normal breast tissues (P <0.05)." (PMID 40230849, 2025).
Infertility (1 paper, 2024). "In line with this, we found that numerous infertility-related DMR-associated genes are expressed during spermatogenesis (e.g., VPS37D, FAM9B [MIM: 300478], SLCO3A1, and CCDC200)." (PMID 38759652, 2024).
cancer (1 paper, 2025). A tumor composed of atypical neoplastic, often pleomorphic cells that invade other tissues. "However, it is important to note that some genes, such as VPS37D and STAD, have different prognostic effects on different types of cancer, which may be because the tumors are not the same (P <0.05)." (PMID 40230849, 2025).
tumor (1 paper, 2025). "Modulation of the expression of VPS37D or other genes within the ESCRT family may result in abnormal ESCRT functions, which could affect tumor cell survival and proliferation." (PMID 40230849, 2025). "Evaluation using StromalScore, ImmuneScore, and EstimateScore indicated that most ESCRT genes, such as VPS37D in DLBC and VPS37B in GBM, exhibited a significant negative correlation with tumor immune infiltration." (PMID 40230849, 2025).
VPS37D also shares sentences with these, for which no sentence is quoted: bladder cancer (1 paper); colorectal cancer (1); gastric cancer (1).